IL6 (interleukin 6)
Diseases named in the same sentence as IL6 in open-access papers (continued):
Sharing a sentence is not in itself a finding about the gene and the disease.
chronic heart failure (continued). "Chlorzoxazone has negative correlation with plasma TNF and IL‐6 levels in patients with congestive heart failure." (PMID 36988255, 2023). "Chronic heart failure (CHF) is characterized by high levels of cytokines, such as IL-6, in an inflammatory state, which may also induce immune aging." (PMID 35924237, 2022). "Finally, based on the previous studies, it seems that moderate- to high-intensity endurance training can reduce IL-6 and TNF-α, and increase IL-10 in elderly healthy and patient with chronic heart failure male individuals." (PMID 33936044, 2021). "In a study that used a walking intervention for chronic heart failure patients for four days in the forest, there was a significant change seen in IL-6 levels, but no significant change was reported in TNF-α levels." (PMID 34444188, 2021). "We additionally identified that short-term endurance training at moderate intensities and the combination of endurance, strength, balance, and flexibility training increase plasma IL-10 and reduce plasma IL-6 and TNF-α in healthy elderly adults and male patients with chronic heart failure." (PMID 33936044, 2021). "In addition, the prognostic role of IL-6 and TNF-α in chronic heart failure patients has been demonstrated in previous studies." (PMID 34685378, 2021). "In patients with chronic heart failure, a nonsignificant increase of IL-6 following exercise has been shown." (PMID 28291817, 2017). "By preventing myocardial hypoxia, ivabradine may diminish the production of cytokines such as IL-6 and TNF-α in congestive heart failure." (PMID 22761780, 2012). "However, in their 2018 study, Mao et al34 reported that forest bathing reduced the level of TNF-α, but not IL-6, in elderly patients with chronic heart failure." (PMID 40673365, 2025). "However, recent data has suggested that inflammatory biomarkers such as IL-6, TNF-alpha, hsCRP, fibrinogen, and BNP are not predictive of intermediate-term risk of ventricular tachyarrhythmias in stable chronic heart failure." (PMID 22203916, 2011). "However, recent data has suggested that inflammatory biomarkers such as IL-6, TNF-alpha, hsCRP, and BNP are not predictive of intermediate-term risk of ventricular tachyarrhythmias in stable chronic heart failure." (PMID 20885777, 2010). "Additionally, multiple studies have shown that as a result of chronic heart failure, the peripheral circulation and the heart are characterized by intense inflammatory responses, with significant elevations of pro-inflammatory cytokines, including TNF-α, IL-1β, and IL-6." (PMID 36361807, 2022). "Finally, it seems that the combination of aerobic, strength, balance, and flexibility exercises based interventions over a long term may be able to reduce CRP, sTNFRII, IL-6, IL-8 and TNF receptors in both older healthy subjects and patients with chronic heart failure." (PMID 33936044, 2021). "On the other hand, Mao et al33 in 2017 reported that forest bathing reduced the level of IL-6, but not TNF-α and CRP in elderly patients with chronic heart failure." (PMID 40673365, 2025).
Hyperinsulinemia (93 papers, 2010 to 2026). An increased concentration of insulin in the blood. "IL-6 can promote the production and secretion of insulin in prediabetes, leading to the occurrence of hyperinsulinemia, which is associated with TNF- α." (PMID 41098781, 2025). "For example, the prototype myokine IL-6 causes hyperinsulinemia, liver inflammation and other systemic alterations." (PMID 35171909, 2022). "The altered microbiome was associated with increased levels of IL6 in the serum, Claudin-2, IL6, and IL1β in the distal intestine with concurrent inflammatory lesions in the liver and hyperinsulinemia." (PMID 32927823, 2020). "In a study of 20 abdominally obese, older women, hyperinsulinemia was positively associated with adipose IL-6 gene expression, but negatively associated with adipose adiponectin expression." (PMID 31660867, 2019). "The present study showed that the HF diet induced an increase of TNF-α and IL-6 pro-inflammatory cytokines plasma level and a decrease of IL-4 and IL-10 anti-inflammatory cytokines plasma level, associated with hyperinsulinemia and a high HOMA-IR index." (PMID 31091691, 2019). "HFD-fed CadKO males showed reduced proinflammatory adipocytokines (TNFα, IL1β, IL6), thus reducing inflammation, macrophage infiltration, and hyperinsulinemia." (PMID 37443781, 2023). "We aimed to determine the risk association of hyperinsulinemia in NMOSD patients with seropositive AQP4-IgG and the serum levels of interleukin (IL)-6 and IL-17A compared with the control group." (PMID 33879088, 2021). "SREBP2 protein levels are elevated in human NASH, possibly due to a direct stimulatory effect of hyperinsulinemia and high levels of circulating and hepatic IL-6 and IL-1β." (PMID 29522534, 2018). "This is evidenced by the non-significant increased level of HDL cholesterol and a declining trend in the levels of hyperinsulinemia, triglycerides, malondialdehyde, and IL-6." (PMID 24608927, 2014). "Fluorescent IHC in the spleen of the dolphin with hyperinsulinemia did reveal abundant staining for IL-6." (PMID 24101915, 2013). "Of the cytokines included herein, IL-6 has been shown to be important in hyperinsulinemia in humans and alterations in levels of IL-6 in the dolphin should be examined further." (PMID 24101915, 2013). "In contrast, sustained hyperinsulinemia (with glucose held at fasting levels) led to a slow and continuous rise in IL-6 beginning after 2–3 hours and continuing at least 6 hours." (PMID 22347395, 2012). "The additional finding that plasma IL-6 also rises in response to both acute hyperglycemic clamp and pulse, as well as hyperinsulinemia highlights the potential role of this cytokine in substrate metabolism." (PMID 22347395, 2012). "Meanwhile, Vx also caused transient hyperinsulinemia at the peak of the LPS-triggered IL-6 increase, but not at the baseline." (PMID 38248469, 2024). "Interestingly, hyperinsulinemia induces the increase in inflammatory cytokines, IL-6 and TNF-α, thereby promoting IR." (PMID 35795140, 2022). "Given the fact that offspring of obese dams exhibit hyperinsulinemia at P2142, insulin and IL-6 signaling might converge on FoxO1." (PMID 35896539, 2022). "Furthermore, hyperinsulinemia increases plasma and cerebrospinal fluid (CSF) concentrations of interleukin-6 and tumor necrosis factor alpha." (PMID 32726329, 2020). "In addition, IL6, IL1B1 and TNF are associated with increased susceptibility to PCOS, and INSR plays a role in compensatory hyperinsulinemia." (PMID 30181771, 2018). "A recent study showed that fructose-enriched diet (for 8 weeks) activates proinflammatory cytokine IL-6, accompanied by a reduction of PPARγ, without causing hyperinsulinemia, in adipose tissue of rats." (PMID 27066503, 2016).
Hyperinsulinemia (continued). "If hyperinsulinemia following an oral glucose load is an important contributor to the early decrease in plasma IL-6 concentrations then this decrease should be attenuated when circulating insulin levels are substantially lower at the same blood glucose concentrations." (PMID 23776669, 2013). "Also, in humans, euglycemic hyperinsulinemia amplifies and prolongs the interleukin 6 (IL-6) response to endotoxin." (PMID 24020899, 2013). "Increased adiposity and hyperinsulinemia has been closely linked to low-grade systemic inflammation in the course of EMS, resulting from the excessive production and release of various adipokines including the proinflammatory cytokines IL-1, IL-6, and the tumor necrosis factor (TNF) α." (PMID 38146533, 2023). "Thus, the systemic hyperinsulinemia together with the increased Il-6 expression may also be driving the enhanced accumulation of lipid in the liver." (PMID 24339864, 2013). "However, the marked increase in IL-6 expression together with a clear delocalization to insulin granules questions the possible involvement of IL-6 in the hyperinsulinemia of fa/fa rats, which deserves to be reassessed in vivo in this model of prediabetic state." (PMID 21826222, 2011). "Thus, chronic activation of monocyte IL-6 production by high levels of fatty acids and hyperinsulinemia in insulin resistant subjects could produce local and systemic inflammation." (PMID 21054880, 2010). "Elevated expression of TNF-α, MCP-1, or IL-6 has been further reported to significantly reduce the expression of GLUT4 and promote the compensatory hyperinsulinemia." (PMID 38146533, 2023). "In T2DM, overweight patients are not only high serum free fatty acids and hyperinsulinemia, but also increased leptin, MCP-1, IL-6, and TNF-α production by adipocytes." (PMID 34003397, 2021). "Inflammatory stimuli, such as IL-6, TNFα, and endotoxin, induce GIP and GLP-1 secretion, leading to hyperinsulinemia in critically ill patients." (PMID 31126070, 2019). "To simulate the effect of hyperinsulinemia we extended the previous network to add the regulation of IL-10 by insulin via the AKT pathway; and the STAT3-signaling cytokines: IL-10, IL-6, and IL-21 all use STAT3." (PMID 28651594, 2017). "Therefore, we hypothesized that maintenance of hyperinsulinemia during HD by either glucose or glucose-insulin infusion would suppress the HD-induced decrease in serum bioactive IGF-I as well as the increase in plasma IL-6." (PMID 23557110, 2013). "The present study investigated the effect of maintaining hyperinsulinemia during HD by either glucose or glucose-insulin infusion on serum bioactive IGF-I and plasma IL-6." (PMID 23557110, 2013). "Changes in metabolic parameters occurred as early as 6-weeks in DIO mice as evidenced by hyperinsulinemia, increased leptin levels and modestly increased levels of pro-inflammatory mediators, including CCL2 and IL-6, in the serum and in the EF pad." (PMID 20445733, 2010). "Our results demonstrated that hyperinsulinemia, coupled with elevated levels of NEFA, generated higher levels of IL-6 production in monocytes compared to the IL-6 response to NEFA alone." (PMID 21054880, 2010). "Inflammatory cytokines produced by the adipose tissue, such as TNF-α (tumor necrosis factor-α) and interleukin-6 (IL-6) have been related to reduce GLUT4 expression, consequently lowering glucose uptake by muscle, and participating on the compensatory hyperinsulinemia." (PMID 22897936, 2012). "Rosiglitazone treatment reduced hyperinsulinemia (DIO 4510 +/− 490 pg/ml: DIO-Rosi 2170 +/− 620 pg/ml), serum CCL2 levels (DIO 84.2 +/− 0.18 pg/ml: DIO-Rosi 47.3 +/− 4.6 pg/ml) and SVF mediator production of IL-6, TNFα, IL-1β and IL-10." (PMID 20445733, 2010).
Hyperinsulinemia (continued). "We previously developed and validated an empirical hypothesis-driven food-based dietary index for hyperinsulinemia and inflammation that were based on habitual diets and strongly predictive of C-peptide and inflammatory markers CRP, IL-6, and TNF-α receptor-2 concentrations." (PMID 36943385, 2023). "Consistent with the proposed elimination of senescent cells, we found no increase in serum IL6, IL8, or VEGF in JAKi-treated patients with hyperinsulinemia, while such an increase was significant in hyperinsulinemia of non-JAKi-treated patients." (PMID 39768214, 2024). "In contrast to the lack of correlation with serum leptin, TNF-α, IL-6, NF-κB and STAT3 activation, hyperinsulinemia in the foz/foz model remained a candidate enhancer of hepatocarcinogenesis." (PMID 30873458, 2016). "Using a more direct approach, hyperinsulinemia, achieved through a six-h insulin infusion, increased circulating TNF and IL-6 concentrations in non-obese mares." (PMID 26486919, 2012). "The down-regulation of TLR4 combined with the lack of increased production of pro-inflammatory cytokines (i.e., IL-6 and TNF-α) and SOCS3 following insulin infusion in the current study suggested that hyperinsulinemia exerts an anti-inflammatory effect on the heart in non-obese individuals." (PMID 25101057, 2014).
insomnia (93 papers, 2013 to 2026). A sleep disorder characterized by difficulty in falling asleep and/or remaining asleep. "(II) The search strategy incorporates multiple synonyms and MeSH terms related to sleep quality, insomnia, sleep disturbances, IL-6, TNF-α, and exercise, thereby reducing the risk of missing relevant studies." (PMID 40729041, 2025). "In summary, we found that acupuncture alleviated insomnia symptoms, reduced peripheral inflammatory markers such as IL-6, and decreased GBC in key regions implicated in neuroinflammation." (PMID 41310834, 2025). "The occurrence of insomnia is associated with the change of the level of oxidative stress and inflammation in vivo, and IL6 as typical inflammatory factors with TVGF good binding energy (−6.09 kcal/mol)." (PMID 39600360, 2024). "Key findings indicate that inadequate sleep and sleep disorders, such as insomnia and obstructive sleep apnea, are associated with elevated levels of pro-inflammatory cytokines like IL-6 and TNF-α, which can impair immune surveillance and promote tumor growth." (PMID 39120277, 2024). "Insomnia means less sleep, which causes the body to produce more interleukin 6 and tumor necrosis factor, and also activates STAT family proteins." (PMID 37334291, 2023). "Okun reported poor sleep quality to be associated with elevated IL-6 levels and symptoms of insomnia and poor sleep quality to be associated with dysregulation of several cytokines." (PMID 37840785, 2023). "The scenario changes radically in pathophysiological conditions such as insomnia, a prevalent sleeping disorder in older adults associated with pro-inflammatory markers IL-6 and C-reactive protein." (PMID 36183306, 2022). "Associations of insomnia symptoms categories with sCD14, IL-6, and D-dimer levels in veterans with HIV in the VACS biomarker cohort (N = 1,542)." (PMID 33561176, 2021). "Although inclusion of insomnia summary data helped in providing some preliminary suggestions on associations between IL-6 and hypersomnia, more detailed investigations disentangling composite symptoms are needed." (PMID 33079133, 2021). "Individuals suffering from insomnia have been shown to have increased levels of daytime and nighttime cortisol as well as increased levels of interleukin-6, which have been linked to neurocognitive impairment." (PMID 32382693, 2020). "Chronic inflammation and oxidative stress are closely linked to insomnia, and Tai Chi can attenuate systemic inflammation by decreasing pro-inflammatory cytokines (e.g., IL-6, TNF-α) and increasing anti-inflammatory cytokines (e.g., IL-10), while enhancing antioxidant defenses." (PMID 41280447, 2025). "OSA, insomnia, and narcolepsy have also been associated with increased serum IL-6 levels." (PMID 35898322, 2022). "Insomnia and sleep deprivation are known to be associated with a low-grade pro-inflammatory state, characterized by the release of acute-phase proteins and cytokines, including IL-1, IL-6, and TNF-α." (PMID 36062000, 2022). "Besides its function in recruiting cells and establishing an inflammatory environment, high levels of IL-6 cause sleep onset insomnia, which could in part explain asymptomatic neurocognitive impairment in HAND." (PMID 28284222, 2017). "In addition, circulating inflammatory mediators such as interleukin-6 (IL-6) may also be involved, as studies in healthy controls have shown that higher concentrations are associated with fatigue, insomnia and sleep deprivation." (PMID 23695990, 2013). "The selected manuscripts were fully reviewed, and data were extracted to evaluate the effects of exercise protocols on sleep quality, insomnia, and inflammatory markers, specifically IL-6 and TNF-α." (PMID 40729041, 2025). "This study was conducted as a systematic review and meta-analysis aimed at evaluating and quantifying the effects of aerobic and anaerobic exercise on sleep quality, insomnia, and inflammatory markers (IL-6 and TNF-α)." (PMID 40729041, 2025).
insomnia (continued). "Previous studies have demonstrated that insomnia patients exhibit elevated levels of IL-6, IL-10, IL-1β, TNF-α, CRP, and other inflammatory markers." (PMID 40636389, 2025). "IL-1β and IL-6, common pro-inflammatory cytokines, were elevated under hypoxia and oxidative stress conditions, leading to insomnia and circadian rhythm disturbances." (PMID 40507808, 2025). "The neuroinflammation-informed GBC-transcriptomic signatures induced by acupuncture were further validated by their significant correlation with reductions in IL-6 levels as insomnia symptoms improved." (PMID 41310834, 2025). "Third, these neuroinflammation-informed GBC-transcriptomic signatures were further validated by their significant correlation with reductions in IL-6 levels as insomnia symptoms improved." (PMID 41310834, 2025). "Although pooled analyses also demonstrated statistically significant improvements in perceived stress, insomnia, quality of life, and IL-6 concentrations, the strength of the current evidence is limited, and the results should be interpreted with caution." (PMID 41221238, 2025). "Cohort analyses in humans reveal that insomnia can significantly elevate IL-6 levels compared to healthy individuals, with gut microbiota diversity positively correlated with both IL-6 levels and sleep duration." (PMID 39035457, 2024). "The study reported that short sleep duration and insomnia symptoms were associated with increases in inflammatory cytokines such as CRP and IL6." (PMID 36849922, 2023). "Nevertheless, we found a significant association between greater sleep fragmentation and IL-6, decreased SWS and TNF-α, and greater insomnia severity, sleep duration, and CRP." (PMID 37081449, 2023). "Comparison of serum IL-6 and IL-8 in 2 groups of patients with insomnia of heart-kidney disharmony type." (PMID 36607882, 2023). "Previous studies have reported associations of insomnia and sleep disturbances with elevated levels of inflammatory biomarkers, including several biomarkers considered in our analyses such as CRP, IL-6 and TNF-α." (PMID 36104003, 2022). "Mean IL-6 levels were significantly higher in patients with insomnia during the presleep period in the afternoon and evening (from 5 p.m. to 11 p.m.)than in controls." (PMID 36329922, 2022). "Insomnia is, in fact, associated with marked decreases in the numbers of T-cells and high levels of CRP and of both IL-6 and TNF." (PMID 35444704, 2021). "Results indicated that sleep disturbance was associated with higher levels of IL-6 and CRP and that short sleep duration, a common consequence of insomnia, was associated with higher levels of CRP." (PMID 36776493, 2020). "Participants with improved insomnia also demonstrated attenuated IL-6 and TNF-α responses to an evoked laboratory pain challenge." (PMID 36776493, 2020). "•Basal/resting levels of cortisol, IL-6, and their interplay at cell level (i.e., GC sensitivity of monocytes) are unchanged in insomnia." (PMID 31236523, 2019). "SKK also regulates plasma interleukin-6 and soluble interleukin-6 receptor concentrations and improves depressed mood in climacteric women with insomnia." (PMID 24790634, 2014). "This study will focus on key serum biochemical markers, including neurotransmitters (5-HT and GABA), inflammatory cytokines (IL-1β, IL-6, TNF-α), and endocrine hormones (melatonin and hormones related to the HPA axis), as these have been implicated in the pathophysiology of insomnia." (PMID 40371071, 2025). "Nevertheless, they suggest that the HRV–insomnia association observed here is unlikely to be mediated solely through CRP- or IL-6–related systemic inflammation." (PMID 41492523, 2025). "Inflammation markers such as CRP,TNF-α, and IL-6 may represent a common physiological process linkingshorter sleep duration and insomnia to mortality." (PMID 39867194, 2025).